CSF1R (colony stimulating factor 1 receptor)
Diseases named in the same sentence as CSF1R in open-access papers (continued):
Sharing a sentence is not in itself a finding about the gene and the disease.
tumor (continued). "Triple combination of a CSF-1R inhibitor, a CXCR2 antagonist, and anti-PD-1 antibody lead to a significant inhibition of tumor growth in several cancer mouse models." (PMID 32509781, 2020). "Selective depletion of TAMs by targeting CSF1R using monoclonal antibodies or small molecule inhibitors has been shown to restrict CSF1R+ TAM accumulation in the TME, leading to reduced tumor growth in a number of mouse models." (PMID 32849557, 2020). "In in vivo PDAC models of mice, macrophages recruitment to the tumor using CSF1R-antagonist GW2580, enhanced the effect of GEM; the presence of TAMs in the tumor seems to convey resistance to GEM by inducing upregulation of the enzyme cytidine deaminase (CDA)." (PMID 32656079, 2020). "For example, dual targeting of suppressive myeloid populations by inhibiting CSF-1/CSF-1R signalling and activation of APCs with CD40 agonists conferred superior anti-tumour efficacy and increased survival compared with monotherapy." (PMID 31973030, 2020). "By genotyping CSF1R methylation in ANTs and tumor tissues of patients with HCC, the level of methylation in ANTs was determined to be significantly higher compared with tumor tissues." (PMID 32724427, 2020). "Evidence that targeting CSF1R and CXCR2 signaling to inhibit TAM and PMN-MDSC expansion, respectively, alongside anti-PD-1 facilitates improved anti-tumor immune responses than either doublet combination." (PMID 32849557, 2020). "In vitro, in vivo, and clinical blockade of macrophage CSF-1R with a monoclonal antibody (RG7155) strongly reduced TAM migration and infiltration into the tumor site and the CD8+/CD4+ T cell ratio." (PMID 32509781, 2020). "Inhibition of CSF1R in neuroblastoma decreased TAM infiltration, improved T cell function, and decreased tumor progression compared to controls." (PMID 33381449, 2020). "Combination treatment of CSF1R blockade with anti-PD1 antibody reprogrammed M2 into M1 and promoted tumor regression in tumor bearing mice." (PMID 32793604, 2020). "The axes of CD47-signal regulatory protein α (SIRPα) and macrophage colony stimulating factor (MCSF)-colony stimulating factor 1 receptor (CSF1-R) between cancer cells and macrophages are important in inhibiting tumor killing by TAMs." (PMID 33348630, 2020). "Again, the depletion of TAMs with a CSF-1R inhibitor, restored CD8 T cell migration and infiltration into tumor islets and improved the efficacy of anti–PD-1 immunotherapies." (PMID 30898166, 2019). "The levels of eight genes (SPI1, RNASE6, C1QB, C1QC, CSF1R, C1QA, TBC1D2, and ATP6V0E1) expression were higher in tumor samples from UALCAN." (PMID 32038997, 2019). "Gene expression of IL- 6, IL-10, CCL2, c-Myc, iNOS, CSF-1R, and MMP9 was elevated in all three of the in vitro TAM preparations which suggests that in vitro generated TAM are immunosuppressive and thus tumor promoting." (PMID 31138333, 2019). "Given that anti-CSF1R blocks both CSF1 and IL34 binding and MC38 tumor cells express both these cytokines, our studies reveal that TAM homeostasis is primarily dependent on CSF1." (PMID 31552020, 2019). "More recently, combination of anti-CSF-1R with docetaxel (microtubule-stabilizing agent) revealed TAM depletion in a murine epithelial ovarian cancer model, in correlation with the anti-tumor effect of docetaxel." (PMID 31547627, 2019). "CSF-1R or CCR2 inhibition, in combination with chemotherapy, resulted in restored CD8+ T cells anti-tumor activity." (PMID 31878087, 2019). "Small molecule inhibitors of CSF-1R reprogram the TME and TAMs, and lead to enhanced T-cell-mediated tumor eradication." (PMID 31439034, 2019). "In animal models, emactuzumab, a humanized mAb targeting CSF-1R, resulted in decreased TAM numbers in the tumor and increased CD8+/CD4+ T cell ratio." (PMID 31878087, 2019).
tumor (continued). "For instance, when two inhibitors of CSF-1R, GW-580 and ARRY-382, were added to the sera of chronic lymphocytic leukemia patients in vitro, it resulted in decreased tumor-supportive macrophages and depleted CD14+ monocytes in the TME." (PMID 31439034, 2019). "In this review, we will focus on small molecule inhibitors of CSF-1R and FAK, and their therapeutic potential as anti-tumor agents and immunomodulators within the TME." (PMID 31439034, 2019). "Flow cytometry analysis of tumor infiltrating T-cells in a murine model of PDAC was performed to investigate the therapeutic effects and mechanism of anti-CSF-1R/anti-PD-1/GVAX combination immunotherapy." (PMID 30424804, 2018). "CSF-1R and CCR2 antagonists have been reported to prevent infiltration of TAMs into the tumor mass increasing response to gemcitabine treatment in mouse models of PDAC." (PMID 30356656, 2018). "Preventing recruitment of macrophages to the tumor site has been achieved through targeting macrophage chemoattractants such as CSF-1 and CCL2 or their corresponding receptors: CSF-1 receptor (CSF-1R) and C-C chemokine receptor type 2 (CCR2)." (PMID 30356656, 2018). "In another study, prolonged CSF1R inhibition led resistance through macrophage-derived IGF1 signaling and PI3K activation in tumor cells." (PMID 29946544, 2018). "Nevertheless, anti-tumor efficacy of the combination of anti-PD-1 antibody, GVAX and anti-CSF1R antibody warrants further investigation in human studies for PDAC." (PMID 30424804, 2018). "Inhibition of CSF-1R can lead to preferential TAM depletion and modulate the remaining myeloid cells toward a more anti-tumor phenotype and away from pro-tumor properties." (PMID 30424804, 2018). "Treatment of GBM with the CSF-1R inhibitor, BLZ945, in transgenic mouse and human xenograft models suppressed tumor growth and improved survival." (PMID 30854331, 2018). "An effective tyrosine kinase inhibitor of CSF-1R such as PLX3397 improved the efficiency of immunotherapy by declining macrophage infiltration and stimulating tumor-infiltrating lymphocytes." (PMID 29450136, 2017). "Apart from combining CSF1R inhibitors with PD1/PDL1 or CTLA4 antagonists, alternative strategies to further enhance anti-tumor efficacy of the host immune system are being investigated." (PMID 28716061, 2017). "From a mechanistic perspective, MMP2, MMP12 and VEGFA, which are produced by macrophages and are important in tumor invasion and angiogenesis, are downregulated upon blockade of the CSF1/ CSF1R axis." (PMID 28467800, 2017). "We next measured whole tumor RNA levels of the chemokine receptors CXCR2 and CSF1R as well as the cognate chemokines for these receptors, CXCL1/CXCL2 and CSF1, respectively." (PMID 28915554, 2017). "78% of patients with evaluable tumor samples showed a significant reduction in CD68+/CD163+ and CSF1R+ macrophages." (PMID 29228548, 2017). "The tyrosine kinase inhibitor of CSF-1R, PLX3397, reportedly improves the efficacy of immunotherapy by decreasing immunosuppressive TAMs in tumor tissues." (PMID 28848446, 2017). "Collectively, our data demonstrate that the addition of a CSF1R inhibitor to anti-VEGF therapy and taxane chemotherapy results in robust anti-tumor effects." (PMID 29228548, 2017). "In human metastatic breast cancer patients the CSF1-R+ myeloid cells showed CSF1-ETS2 induced higher expression of miR-21 and miR-29a which correlated with higher metastatic tumor burden." (PMID 28197019, 2017). "We quantified changes in tumour burden and TAM density in a KP pulmonary tumour model, as well as a GFP-labelled KP model in response to CSF-1R blockade." (PMID 28176769, 2017). "First, we evaluated the effect of the CSF1R inhibitor, AC708, on tumor burden in the IG10 syngeneic mouse model." (PMID 29228548, 2017). "C57BL/6 mice with established subcutaneous SM1 tumors were treated with the CSF-1R inhibitor PLX3397 and the BRAF inhibitor PLX4032 daily once tumor diameter reached ~5 mm." (PMID 25939769, 2015).
tumor (continued). "To evaluate functional interactions mediated by the receptor, we also compared the levels of CSF1R and CSF1 ligand in cHL cell lines and tumours using Q-PCR." (PMID 26066800, 2015). "This process involves paracrine signaling between RTKs (e.g., colony stimulating factor-1 receptor: CSF1R) on macrophages and EGFR on tumor cells." (PMID 25243094, 2014). "Additional repressed genes were ANGPTL2, TGM2, IL-6, CSF1R, TNFSF12 as well as a key regulatory MAP kinase ERK1/2 (MAPK3), all known to stimulate chronic inflammatory signaling in the tumor microenvironment and to promote cancer metastasis." (PMID 24498382, 2014). "Immunohistochemistry was used to evaluate the expression of CD68, M-CSF, CSF-1R, CD57, TGF-beta and Ki67 in tumor and peritumoral capsule." (PMID 22554285, 2012). "Since we detected a 10-fold increase in CSF-1R-dependent phosphorylation of UQCRC2, this raises that possibility that this modification may downregulate it's activity, thus causing a similar loss of activity as observed in tumor cells with lower levels of UQCRC2 expression." (PMID 21049007, 2010). "The other target genes, FLT3, CSF1R, PDGFRB, AXL and MET showed lower expression levels in the tumor tissue compared to normal tissue except AXL in NF1 associated GIST." (PMID 21171987, 2010). "Finally, in a mouse metastasis model, blocking the CSF1/CSF1R axis with a CSF1R inhibitor reduced the M2-like TAMs recruitment and CRC tumor metastasis burden." (PMID 41639044, 2026). "Indeed, macrophage depletion via anti-CSF1R mAb or clodronate liposomes significantly decreased the number of cells expressing CXCL1/2 and CFB in tumor, as well as the levels of C3a and C5a." (PMID 41480760, 2026). "Primary tumor growth and invasion were inhibited in Csf1rCreCxcr4fl/fl mice compared to their littermate without Csf1r-dependent Cre expression (Cxcr4fl/fl mice)." (PMID 40756343, 2025). "Notably, concurrent inhibition of IGF-1/PI3K and CSF-1R using Linsitinib (OSI906) and Sotuletinib (BLZ945) has shown promising results, significantly extending median survival in preclinical models until tumor recurrence." (PMID 40427130, 2025). "A synthesized compound 21 from a series of (Z)-1-(3-((1H-pyrrol-2-yl)methylene)-2-oxoindolin-6-yl)-3-(isoxazol-3-yl)urea derivatives exhibits excellent CSF-1R inhibitory activity (IC50 = 2.1nM), promoting M1 macrophage infiltration and enhancing anti-tumor immune responses." (PMID 40873588, 2025). "Among the known receptors of IL34, Csf1r was predominantly expressed in the immune cluster, indicating that the IL34-CSF1R axis could be responsible for the regulation of the tumor immune microenvironment." (PMID 40538439, 2025). "Thus, blocking colony-stimulating factor 1 receptor (CSF1R) reduces monocytes/macrophages early in tumorigenesis and restrains PNF growth, yet the same approach later in tumor development supports tumor expansion." (PMID 40992926, 2025). "For instance, CSF1R inhibitors such as BLZ945 demonstrated significant TAM depletion but failed to induce sustained tumor regression unless combined with radiotherapy or immune checkpoint blockade." (PMID 40867316, 2025). "To further establish that CSF-1R signaling between tumor cells and macrophages was important for increasing tumor cell migration across the endothelial cell layer, we used BMMs lacking CSF-1R (Csf1r−/−) in the iTEM assay." (PMID 40646332, 2025). "CSF-1 could affect the proliferation of CSF-1R-expressing cells and promote M2 polarization of macrophages.761,1078 pIL-12 + PLX@cR-PssPD could disintegrate at the tumor site and release CSF-1R inhibitor PLX3397 (PLX) and pIL-12." (PMID 40055311, 2025). "Moreover, combining CSF-1R inhibition with other treatments yields better outcomes, enhancing CD8+ T-cell infiltration and slowing tumor progression, especially when coupled with anti-PD-1 therapy." (PMID 40079009, 2025).
tumor (continued). "Recent studies suggested that targeting TAMs’ phenotypic reprogramming, using agents like CSF-1R inhibitors or CD40 agonists, can boost their antigen-presenting efficiency and activate anti-tumor T-cell responses, offering a novel strategy for HCC immunotherapy." (PMID 41361104, 2025). "On the other hand, inhibiting CSF-1R promotes the infiltration and activation of CD3 + CD8 + T cells in the tumor microenvironment, suppresses tumor immune escape, and enhances the antitumor activity of PD-1/PD-L1 inhibitors, thereby overcoming resistance to PD-1/PD-L1 axis blockade." (PMID 41247642, 2025). "Depleting non-cytotoxic macrophages using CSF1R inhibition while preventing ATG9A-mediated tumor membrane repair enhances the anti-tumor activity of therapeutic antibodies in mice." (PMID 40595560, 2025). "Additionally, although the M1/M2 classification is widely employed in tumor-related research, particularly those investigating the CSF1/CSF1R axis." (PMID 40287444, 2025). "In vivo administration of the CSF1R inhibitor pexidartinib (PLX3397) depleted M2-polarised macrophages, increased intratumoural CD8+ T-cell density and suppressed both primary tumour growth and pulmonary dissemination in orthotopic and patient-derived xenografts of osteosarcoma." (PMID 41142827, 2025). "To further explore the resistance mechanism of anti-CSF-1R therapy in GBM, we applied translatome profiling in a highly refractory G422TN-GBM mouse model, which accurately replicates the therapeutic responses and tumor recurrence of human GBM." (PMID 41365876, 2025). "Finally, it also targets immune suppression within the tumor microenvironment by inhibiting colony-stimulating factor 1 receptor (CSF1R), which can enhance anti-tumor immunity." (PMID 40149618, 2025). "Moreover, using IF, we determined the specific topography of CD20+ tumor cells (intra-T area) and of CD68+CD86+ M1 and CD68+CSF1-R+ M2 macrophages (peri-T area) in DLBCL samples." (PMID 41415285, 2025). "Because CSF1/CSF1R signalling drives PVNS and targeted inhibitors such as vimseltinib achieve significant tumour regression and functional improvement, similar targeted approaches might be explored for diffuse synovial proliferative disorders." (PMID 41409756, 2025). "Blockade of CSF1R using small-molecule inhibitors, such as BLZ945, has shown efficacy in glioma, where treatment led to TAMs with increased expression of antigen presentation genes and downregulation of pro-tumour macrophage markers." (PMID 40948757, 2025). "TREM2 is expressed on CSF1R+ TAMs and modulated by CSF1, suggesting that dual inhibition of CSF1R and TREM2 may further potentiate macrophage repolarization and tumor immune surveillance." (PMID 40330466, 2025). "Additionally, the combination of anti-PD-1 and CSF-1R inhibition (PLX3397) with an adenovirus, Ad5-hTERT-E1A, increased tumor control in CRC mouse models." (PMID 41440025, 2025). "CSF-1R inhibitors, such as IMC-CS4, target the colony-stimulating factor 1 receptor on macrophages, depleting protumor TAM subsets and reprogramming remaining macrophages to bolster tumor-suppressing immunity." (PMID 40458409, 2025). "Although CSF1R inhibitors can cross the BBB and reduce MDM at the tumor sites, they may inadequately penetrate the tumor margins and surrounding normal brain tissue, leaving these regions susceptible to recurrence." (PMID 40800581, 2025). "For instance, encapsulating CSF1-R and IDO inhibitors, the tumor acidity-responsive nanovaccine sheds its PEG shell under acidic conditions, reducing size and increasing positive charge to enhance tumor penetration." (PMID 40083941, 2025). "Despite the promising preclinical studies using CSF-1/CSF-1R inhibitors in combination with chemotherapy, immunotherapy, or radiotherapy, phase II clinical trials have not yielded the same anti-tumor efficacies." (PMID 40646332, 2025).
tumor (continued). "Notably, tumor-specific intercellular signaling pathways, such as CSF1/CSF1R and CXCL/ACKR1, were identified, highlighting their potential role in fostering an immunosuppressive TME." (PMID 40438108, 2025). "In murine BC models, the inhibition of CSF1/CSF1R signaling through either CSF1 monoclonal antibodies or the CSF1R tyrosine kinase inhibitor PLX3397 results in the depletion of TAMs and significantly postpones tumor recurrence following radiotherapy." (PMID 40092996, 2025). "The inhibition of CSF-1R reduced the infiltration of macrophages at the tumor site, inhibited the activity of CD8+T cells by M2 macrophages, and enhanced the migration and infiltration of CD8+T cells into tumor islets." (PMID 38787372, 2024). "In the context of this partial microglial depletion, neither hippocampal neurogenesis nor spatial memory performance were rescued by CSF1R inhibition following tumor-clearing CAR T cell therapy for DIPG or ALL." (PMID 38798554, 2024). "Notably, either CSF-1R or EGFR inhibition signaling completely stop invasion of both TAMs and tumor cells." (PMID 39588367, 2024). "We show that tumor cells have an increased expression of several markers (CD47, IL7R, NKG7, CD80, CD84, CSF1R, NLRC5/CITA, CD2 and IRF3) that may be involved in regulating the level of immune infiltration and the effect on tumor immunity." (PMID 39001353, 2024). "The function of these cells can be critical in tumor progression and shaping the TME, but how the CSF-1R contributes to these particular cell pools remains unclear." (PMID 39457693, 2024). "Understanding the diverse roles of the CSF-1R in the TME underscores its potential as a therapeutic target for cancer treatment, aiming at disrupting pro-tumorigenic cellular crosstalk and enhancing anti-tumor immune responses." (PMID 39457693, 2024). "To understand whether the reduced T cells infiltration of SEMA3Ahigh tumours was due, at least in part, to the abundance of TAM at the tumour bed, we targeted macrophages using a monoclonal antibody against CSF1R (αCSF1R)." (PMID 38670629, 2024). "In addition, CSF1R inhibition was also combined with anti-angiogenic therapy using cediranib (a VEGFR2 inhibitor), reducing cell proliferation and altering the tumor morphology." (PMID 38665919, 2024). "Other animal experiments demonstrated that the introduction of CSF-1R inhibitors after anti-VEGF drug resistance reduced the tumor size to little or no measurable degree in high-grade serous ovarian cancer." (PMID 38787372, 2024). "Therefore, the encouraging antitumor activity of sulfatinib for NETs is achieved by preventing tumor angiogenesis and tumor immune evasion through simultaneous FGFR, CSF-1R, and VEGFR inhibition." (PMID 38172256, 2024). "Furthermore, the injection of LNCs@CSF1R siRNA increased the production of effector cytokines IFNγ and GzmB by CD8 + T cells within the tumor." (PMID 38992688, 2024). "Another study, which used CRISPR-Cas9 CSF-1 knockout murine breast (4T1) and colon (MC38) carcinoma models, showed that the inhibition of CSF-1R signaling boosts an immune-permissive TME, and results in improved tumor control compared to mice with parental tumors." (PMID 39457693, 2024). "The activation of the CSF-1R by its ligands, colony-stimulating factor 1 (CSF-1) and Interleukin-34 (IL-34), regulates TAM polarization towards an immunosuppressive M2 phenotype, promoting tumor progression and immune evasion." (PMID 39457693, 2024). "By contrast, anti-CSF-1R treatment did not reduce the effects of anti-PD-L1 + anti-TIGIT treatment on tumour Treg cells, suggesting an alternative mechanism of action." (PMID 38418879, 2024).